TTC28 (tetratricopeptide repeat domain 28)
Description:
During mitosis, may be involved in the condensation of spindle midzone microtubules, leading to the formation of midbody.
Synonyms: KIAA1043; TPRBK
Tractability: PROTAC: ubiquitination databases record sites on it; its protein half-life has been measured.
Gene: Protein-coding gene on chromosome 22 (27,978,014 to 28,679,840, reverse strand). Ensembl gene ENSG00000100154.
Subcellular location: Cytoplasm, cytoskeleton; Cytoplasm, cytoskeleton, microtubule organizing center, centrosome; Cytoplasm, cytoskeleton, spindle; Cytoplasm, cytoskeleton, spindle pole; Midbody
Subcellular location (Human Protein Atlas): Cytokinetic bridge; Microtubules; Mitotic spindle; Cytosol
Gene Ontology:
Molecular function: kinase binding
Biological process: regulation of mitotic cell cycle
Cellular component: midbody; centrosome; cytoskeleton; spindle; spindle pole
Genetic constraint (gnomAD): Loss-of-function variants: 63 observed, 201.55 expected, observed/expected ratio (o/e) 0.31, 90% interval 0.25 to 0.39. The upper end of that interval is the gene's LOEUF score, 0.39, which puts it in group 1 of 6, group 1 being the genes least tolerant of losing a copy. Missense variants: 2,677 observed, 3,216 expected, observed/expected ratio (o/e) 0.83, 90% interval 0.81 to 0.86. Synonymous variants: 1,171 observed, 1,317.4 expected, observed/expected ratio (o/e) 0.89, 90% interval 0.85 to 0.93.
Homologues: Orthologues: chimpanzee TTC28 (99% identical), macaque TTC28 (99% identical), dog TTC28 (94% identical), mouse Ttc28 (90% identical), rat Ttc28 (90% identical), rabbit TTC28 (89% identical), pig TTC28 (88% identical), tropical clawed frog ttc28 (83% identical), guinea pig TTC28 (81% identical), zebrafish TTC28 (74% identical), Drosophila melanogaster CG43163 (44% identical). Paralogues in human: GPSM2 (9% identical), GPSM1 (8% identical), TTC24 (4% identical), RAPSN (4% identical), TTC29 (4% identical), GPSM3 (2% identical).
Diseases named in the same sentence as TTC28 in open-access papers:
TTC28 is named in the same sentence as 18 diseases in open-access papers, as found by Europe PMC text mining. Sharing a sentence is not in itself a finding about the gene and the disease. The quoted sentences say what the papers report.
meningioma (2 papers, 2012 to 2025). A generally slow growing tumor attached to the dura mater. "In conclusion, the identification and validation of TRPC6, XBP1 and TTC28 as potential targets for meningioma therapy represent a significant advancement in our understanding of the disease and open new avenues for therapeutic interventions." (PMID 40046334, 2025). "In meningioma, TTC28 is significantly upregulated in tissue stem cells, endothelial cells and chondrocytes." (PMID 40046334, 2025). "The odds ratios (ORs) of these genes were significantly high, indicating a positive causal relationship with meningiomas (TRPC6: ORIVW = 2.11; XBP1: ORIVW = 1.40; TTC28: ORIVW = 1.93 and ODF3: ORWald ratio = 4.76)." (PMID 40046334, 2025). "The results indicated that the expression of these four genes is causally stable in meningiomas (TRPC6: PIVW = 1.09×10−7; XBP1: PIVW = 4.28×10−11; TTC28: PIVW = 7.92×10−5; ODF3: PWald ratio = 7.94×10−8)." (PMID 40046334, 2025). "By extracting specific cells in which the four prioritized genes were expressed, we validated the high expression of XBP1, TTC28 and TRPC6 in meningioma tissues." (PMID 40046334, 2025). "The integration of bulk and single-cell RNA sequencing confirmed the upregulated expression of three of the genes (XBP1, TTC28 and TRPC6) in meningioma tissues, unravelling their cellular distribution and hinting at the tumour’s intrinsic heterogeneity." (PMID 40046334, 2025). "We focused on differences in the expression of the four identified genes (XBP1, TTC28, TRPC6 and ODF3) between meningioma and normal brain tissues." (PMID 40046334, 2025). "In this study, we performed SMR, colocalization and MR analyses using meningioma summary statistics from FinnGen r9 and eQTL data from eQTLGen, and identified XBP1, TTC28, TRPC6 and ODF3 as potential therapeutic gene targets for meningioma." (PMID 40046334, 2025).
carcinosarcoma (1 paper, 2024). A malignant tumor composed of a mixture of carcinomatous and sarcomatous elements. "TTC28-MECOM fusion may modulate the carcinosarcoma phenotype in ECS carcinogenesis; however, this requires functional verification in future studies." (PMID 39158654, 2024).
ciliopathies (1 paper, 2019). "We prioritized TTC28 because variants in TTC7A (OMIM: 609332), a member of the same gene family, causes autosomal recessive gastrointestinal defects, and variants in TTC21B (OMIM: 612014) are reported in human ciliopathies." (PMID 30679815, 2019).
diabetes (1 paper, 2013). "Of note, the Tmem229B, Prss53 and Ttc28 genes, which have not been linked to β-cell functions or diabetes, showed strong signals in untreated islets but were strongly suppressed by STZ." (PMID 23828045, 2013).
glioma (1 paper, 2022). A benign or malignant brain and spinal cord tumor that arises from glial cells (astrocytes, oligodendrocytes, ependymal cells). "SNHG18, NEAT1, LINC00339) and low expression of four lncRNAs (DICER1.AS1, NNT.AS1, WAC.AS1, TTC28.AS1 were with poor prognosis in glioma." (PMID 35237509, 2022).
melanoma (1 paper, 2023). A malignant, usually aggressive tumor composed of atypical, neoplastic melanocytes. "Aberrant expression of TTC28 and EXOC1 is associated with melanoma and platelet secretion defects, respectively." (PMID 37026480, 2023).
prostate carcinoma (1 paper, 2022). A carcinoma that arises from epithelial cells of the prostate gland. "In addition to alterations in highly validated prostate cancer genes, we identified highly recurrent rearrangements near or involving genes that have not been extensively studied in prostate cancer in multiple cohorts, such as LSAMP, PTPRD, and TTC28." (PMID 35943799, 2022).
tumor (8 papers, 2012 to 2025). "Its involvement in microtubule stabilization suggests that TTC28 may contribute to tumour cell proliferation and chromosomal stability during cell division." (PMID 40046334, 2025). "In endothelial cells, TTC28 upregulation may contribute to neoangiogenesis, which is essential for tumour growth and metastasis." (PMID 40046334, 2025). "In tissue stem cells, the high communication activity of CD99 may be associated with cell migration and invasiveness in the tumour microenvironment, promoting tumour cell spread and metastasis, suggesting that XBP1, TRPC6 and TTC28 may promote tumour development." (PMID 40046334, 2025). "The high interaction of tissue stem cells with collagen may affect the tumour microenvironment by promoting extracellular matrix synthesis and degradation, and influencing tumour growth and angiogenesis, suggesting that XBP1, TRPC6 and TTC28 may influence tumour growth and angiogenesis." (PMID 40046334, 2025). "The role of FN1 in tissue stem cells with high communication intensity may facilitate interactions with other cells in the tumour microenvironment by supporting tumour cell attachment and spread, suggesting that XBP1, TRPC6 and TTC28 may influence the tumour microenvironment." (PMID 40046334, 2025). "Conversely, we found the previously identified PCa driver gene LRP1B (12/17) and new candidate genes TTC28 (16/27), CADM2 (12/16), LSAMP (11/16), EYS (16/18), PTPRD (12/18), PACRG (5/6) and PDE4D (12/17) to be predominately interrupted in tumours from African patients." (PMID 36045381, 2022).
cancer (1 paper, 2022). A tumor composed of atypical neoplastic, often pleomorphic cells that invade other tissues. "Furthermore, the expression of top 5 genes (DCHS1, PRKG1, TGFBR2, TNS1, and TTC28) in the majority of detailed cancer types was shown in the form of heatmap." (PMID 36051999, 2022).
TTC28 also shares sentences with these, for which no sentence is quoted: breast carcinoma (1 paper); colorectal cancer (1); COVID-19 (1); depression (1); glaucoma (1); infection (1); leiomyoma (1); lymphoma (1); myeloid leukemia (1).